ERO1A (endoplasmic reticulum oxidoreductase 1 alpha)
Diseases named in the same sentence as ERO1A in open-access papers (continued):
Sharing a sentence is not in itself a finding about the gene and the disease.
tumor (continued). "Considering our findings, overactivated mTORC1 likely facilitates the expression of IL-6 through upregulation of ERO1α, thus promoting cell proliferation and tumor growth in the TSC." (PMID 38610018, 2024). "Conversely, ERO1α overexpression-induced xenograft tumor development and ferroptosis inhibition were significantly attenuated with suppression of SLC7A11." (PMID 38610018, 2024). "The mediation effect of SLC7A11 on ERO1α-regulated cell growth and angiogenesis was further verified in vivo using a subcutaneous xenograft tumor model." (PMID 38610018, 2024). "Our results indicate that ERO1α promotes tumor progression and ferroptosis resistance, at least partially, by upregulating SLC7A11." (PMID 38610018, 2024). "Second, the anti-ferroptosis role of ERO1α was further confirmed by the observation that inhibition of ferroptosis using Lip-1 partly rescued ERO1α depletion–mediated suppression of tumor growth and upregulation of MDA." (PMID 38610018, 2024). "Because aberrations in the PI3K/AKT/mTORC1 pathway are common in PDAC and TNBC, it is likely that hyperactivated mTORC1 in these cancers upregulates ERO1α expression and then promotes tumor progression." (PMID 38610018, 2024). "Consistent with our in vitro observations, ERO1α knockout NTC/T1 cells were more sensitive to IKE-induced tumor suppression than control cells in vivo." (PMID 38610018, 2024). "Recently, the crucial role of ERO1α in tumor progression and treatment has been illustrated in many types of human cancers." (PMID 38610018, 2024). "ERO1A expression has been shown to be a poor prognostic indicator across multiple tumor types including lung, pancreatic, hepatocellular carcinoma and multiple myeloma." (PMID 39496753, 2024). "In summary, we have demonstrated that aberrantly activated mTORC1 contributes to ferroptosis resistance and tumor growth by regulating of the ERO1α/IL-6/STAT3/SLC7A11 signaling pathway." (PMID 38610018, 2024). "Together, these data indicate that the role of ERO1A in modulating the secretome is likely multifactorial but has the potential to shift the surrounding tumor microenvironment in favor of growth." (PMID 39496753, 2024). "Our findings correlate with the results of previous studies, suggesting that ERO1α is critical for cell proliferation and angiogenesis and unveiling a new molecular link between mTORC1 activation and tumor development." (PMID 38610018, 2024). "Our work supports the role of ERO1A in modulating the tumor microenvironment that is likely to contribute to tumor progression." (PMID 39496753, 2024). "Consistent with the in vitro results, SLC7A11 re-expression abrogated the suppressive effects of ERO1α depletion on xenograft growth, tumor cell proliferation (as assessed by the Ki-67 index), and tumor angiogenesis (as assessed by the CD31 index)." (PMID 38610018, 2024). "During ER stress, the expression of endoplasmic reticular oxidoreductase-1α (ERO1A) increases, contributing to tumor cell survival." (PMID 37769655, 2023). "We previously identified ERO1a to be hypoxia-inducible and involved in tumor formation, where genetic deletion of ERO1a in PDAC tumors reduced PD-L1 expression and prevented tumor formation in vivo." (PMID 38187398, 2023). "Transduction of mouse ERO1A cDNA completely rescued the growth defects of Ero1aKO MC-38 tumors during six rounds of aPD-1 treatment compared with those transfected with empty vector, suggesting the in vivo synergistic anti-tumor role of ERO1A ablation." (PMID 37769655, 2023). "To understand the synergistic anti-tumor effects induced by the deletion of ERO1A in tumors, we compared the transcriptomes of identified tumor clusters from Ero1aWT and Ero1aKO tumors based on scRNA-seq analyses." (PMID 37769655, 2023). "Their respective roles in myeloid cell infiltration were demonstrated with ERO1a modulating the hypoxic tumor compartment and IDO1 modulating the myeloid cell compartment." (PMID 38187398, 2023).
tumor (continued). "Ablation of ERO1A in tumor cells substantially incites anti-tumor T cell immunity and promotes the efficacy of aPD-1 in therapeutic models." (PMID 37769655, 2023). "They find that targeting ERO1A can incite anti-tumor immunity and enhance aPD-1 efficacy in therapeutic models." (PMID 37769655, 2023). "Collectively, these results suggest that ERO1A deletion triggers lethal ER stress responses in tumors and promotes host anti-tumor immunity via ICD." (PMID 37769655, 2023). "Previous studies have stated that tumor angiogenesis was promoted by ERO1A via regulating the expression of VEGFA." (PMID 34712608, 2021). "Endoplasmic reticulum oxidoreductase 1 alpha (ERO1L) serves as an effector for tumor growth in human malignancies." (PMID 33681386, 2021). "After accumulation of tumor cell-conditioned medium from HCT116 cells with knockdown of ERO1A, PPARδ and the both genes, the tumor cell-conditioned medium was mixed to that of HUVECs." (PMID 34712608, 2021). "As IO approaches move toward combination strategies, it is essential to determine the effect of modulating novel targets such as Ero1α on the immune tumor microenvironment." (PMID 33615311, 2020). "Recent evidence indicates that ERO1α expression in tumor cells is a critical determinant of metastasis." (PMID 33615311, 2020). "Because inhibiting Ero1α is likely to change the cytokine and chemokine profile of the tumor microenvironment, further studies are required to fully understand the effect of inhibiting Ero1α on tumor mediated immune suppression." (PMID 33615311, 2020). "Since tumour spheres simulate the actual tumour hypoxic microenvironment, we analysed the expression and localisation of ERO1α and CA9 in tumour spheres obtained from HCT116 and HeLa cells through sphere formation assays." (PMID 31142270, 2019). "Using DCFDA assays to quantify ROS levels in hypoxic tumor cells, we observed that ERO1α-KO clones displayed a significant reduction in ROS generation relative to WT clones." (PMID 31666928, 2019). "The resulting tumour xenografts were subsequently analysed by immunohistochemistry using antibodies specific for ERO1α and CA9, and the localisation of the proteins was compared to the staining with pimonidazole." (PMID 31142270, 2019). "We recently found that repression of ERO1α produced potent anti-tumor immunity of healthy CD8 T cells." (PMID 31779147, 2019). "Nevertheless, our observations reinforce the importance and usefulness of ERO1α as a prognostic marker in cancer since hypoxia affects both cancer cells and the tumour microenvironment and plays a pivotal role in the process of cancer progression." (PMID 31142270, 2019). "When analyzed by western blot, key EMT suppressor E-cadherin was found to be highly expressed in ERO1α-KO tumor cells, perhaps explaining their reduced migratory potential in our functional assays." (PMID 31666928, 2019). "Collectively, we believe that the expression of ERO1α is independent of the specific cancer cell line or cancer type and that ERO1α is a reliable marker for the identification of hypoxic tumour microenvironments." (PMID 31142270, 2019). "Analysis of clinical data revealed that increased levels of ERO1α correlated with poor prognostic features such as tumor vascular invasion, advanced tumor pathologic stage, and tumor TNM stage." (PMID 30377291, 2018). "Most importantly, ERO1α knockdown significantly repressed the death of HCC xenograft mouse models by reducing tumor distant metastasis, and host angiogenesis by suppressing the expression of S1PR1, p-STAT3, and VEGF-A in HCC cells." (PMID 30377291, 2018). "The group overexpressing ERO1α overexpression enhanced the capability of tumor cells to prompt tube formation by HUVECs." (PMID 30377291, 2018). "Taken together, these results suggest that ERO1α enhanced the ability of tumor cells to promote HUVEC tube formation." (PMID 30377291, 2018).
tumor (continued). "Another mechanism by which Ero1α contributes to evasion of tumor cells from immune responses is by promoting infiltration of myeloid-derived suppressor cells (MDSCs) into the tumor." (PMID 29673197, 2018). "At the same time, several lines of evidence suggest, that Ero1α facilitates evasion of tumor cells from host immune responses and tumor vascularization." (PMID 29673197, 2018). "Our findings revealed that ERO1α overexpression in HCC cells enhanced the capability of tumor cells to promote HUVEC migration and tube formation in vitro." (PMID 30377291, 2018). "The results suggest that targeting ERO1-α in tumor cells can be a novel approach for cancer immunotherapy." (PMID 28160557, 2017). "We found that elevated ERO1A, OSBPL3 and IFI44L protein expression in tumor tissues was significantly associated with late T stage which represent depth of tumor invasion and late TNM stage." (PMID 28881752, 2017). "We found that ERO1α plays a critical role in integrin glycosylation and membrane transport in hypoxic tumour cells, and that ERO1α deletion leads to attenuated integrin signalling, including in tumour growth and epithelial-mesenchymal transition (EMT)." (PMID 28839225, 2017). "Here, we have revealed a previously unrecognized pathway through which ERO1α can potentially modulate tumour cell behaviour under hypoxia and thus favour cancer progression." (PMID 28839225, 2017). "Among oxidoreductases, ERO1-α is unique, because it is upregulated within tumor cells and under the condition of hypoxia." (PMID 28160557, 2017). "Therefore, ERO1α has a complex role in immunosuppression and potential as a target for tumor immunotherapy." (PMID 41333024, 2025). "Overall, these findings demonstrate that ERO1α expression promotes tumor-suppressive microenvironment via recruitment and accumulation of PMN-MDSC cells mainly by facilitating proper protein folding of cytokines needed for recruitment of PMN-MDSC cells such as G-CSF, CXCL1 and CXCL2." (PMID 41226317, 2025). "Therefore, high ERO1α expression is strongly associated with EMT and increased tumor aggressiveness, metastatic potential, and poor patient prognosis." (PMID 41333024, 2025). "ERO1α directly promotes tumor phenotypes by regulating multiple signaling pathways." (PMID 41333024, 2025). "Furthermore, because of its several tumor-promoting roles, it is crucial to prioritize the development of selective and potent ERO1α inhibitors." (PMID 41226317, 2025). "On the contrary, knock-down of ERO1α results in enhanced anti-tumor immunity." (PMID 41226317, 2025). "Additionally, ERO1A influences immunogenic cell death in tumor cells by regulating the balance between IRE1α and PERK signaling, attenuating the therapeutic efficacy of PD-1 blockade." (PMID 41407677, 2025). "This suggests that ERO1α’s regulation under hypoxia is cell-type dependent, possibly influenced by the presence of specific hypoxia-inducible factors (HIFs) or variations in the tumor microenvironment." (PMID 41226317, 2025). "Elevated ERO1α expression may contribute to tumor adaptation by influencing protein folding efficiency, modulating stress response pathways, and promoting interactions between cancer cells and their microenvironment." (PMID 41226317, 2025). "The role of ERO1α appears to become even more significant in a hypoxic tumor microenvironment." (PMID 41226317, 2025). "Moreover, authors have also investigated mechanisms of how ERO1α induces accumulation of PMN-MDSCs within the tumor." (PMID 41226317, 2025). "Emerging evidence indicates that ERO1α contributes to cancer stem cell maintenance and therapy resistance, and its regulation through DNA methylation provides a mechanistic link consistent with observations across diverse tumor contexts." (PMID 41226317, 2025). "This immunomodulatory role of ERO1α positions it as a central mediator of tumor immune evasion." (PMID 41226317, 2025).
tumor (continued). "Consequently, ERO1α inhibition represents a promising strategy for selective tumor cytotoxicity with minimal toxicity to normal cells." (PMID 41333024, 2025). "Therefore, ERO1α+ tumor cells secrete G-CSF, which acts as a proliferation factor for PMN-MDSC cells as well as CXCL1 and CXCL2, which stimulate PMN-MDSC cells recruitment from the circulation into the tumor stroma." (PMID 41226317, 2025). "Depletion of ERO1A resulted in less overall tumor burden and reduction in number of nodules." (PMID 39496753, 2024). "Previous studies have demonstrated that ERO1α is involved in tumor angiogenesis." (PMID 38610018, 2024). "Despite the redundancy in oxidative protein folding within the ER of mammalian cells, cancer cells appear to have an increased dependency on ERO1A which maybe more appreciable in the context of the tumor microenvironment or potentially drug response." (PMID 39496753, 2024). "Because Tsc1 − / − or Tsc2 − / − MEFs have low tumorigenic ability in vivo, we constructed a novel cell line (NTC/T1 null cells) with potent tumorigenicity derived from a subcutaneous tumor formed by the injection of Tsc1 − / − MEFs into nude mice to investigate the in vivo role of ERO1α." (PMID 38610018, 2024). "In addition, ERO1A mRNA level was negatively correlated with genes that define anti-tumor immunity and immune infiltrates, including CD8+ T, B, and NK cells, whereas it was positively correlated with CD4+ T cells." (PMID 37769655, 2023). "In addition, co-culturing of CD8+ T cells with tunicamycin pre-treated Ero1aKO tumor cells showed significant increase in the release of IFN-γ, TNF-α, and GzmB compared with controls, indicating that tumor ERO1A induces T cell dysfunction." (PMID 37769655, 2023). "Given the distinct influence of ERO1a inhibition on the hypoxic tumor secretome and the greater impact of IDO1 inhibition on myeloid signaling, the combined effect of ERO1a and IDO1 inhibition at the same single treatment concentration was investigated for their immune-related biological pathways." (PMID 38187398, 2023). "Whether ERO1A signaling affects anti-tumor immunity and clinical outcomes in patients with solid tumors remains unknown." (PMID 37769655, 2023). "We show that disruption of ERO1A may trigger a lethal ER stress response in tumor cells and promote host anti-tumor immunity via ICD." (PMID 37769655, 2023). "Furthermore, PERK activation upregulates ERO1A and facilitates protein folding, alleviating ER stress and thus maintaining tumor survival." (PMID 37769655, 2023). "Finally, we used the ssGSEA method to determine the correlations between ANLN, POLR3G, EHBP1, and ERO1A and 24 types of tumor-infiltrating immune cells." (PMID 35769906, 2022). "Ablation of ERO1-α causes significantly reduced PD-L1–mediated T-cell apoptosis, indicating ERO1-α may be involved in tumor-mediated immunosuppression." (PMID 33634130, 2021). "However, the impact of increased ERO1α expression in tumor cells extends into the tumor microenvironment." (PMID 33615311, 2020). "ERO1A, showed differential expression across sexes, tumor stages and T stages." (PMID 31938577, 2020). "Indeed, when skin was excised from the injection sites we were unable to detect significant tumor development in any mice that had received ERO1α-KO PDA cells." (PMID 31666928, 2019). "We subsequently investigated the possible co-localisation of ERO1α and pimonidazole by immunofluorescence staining and observed a strong and largely overlapping fluorescent signal for ERO1α and pimonidazole in the central necrotic part of the tumour." (PMID 31142270, 2019). "Similarly, when we assessed the motility of ERO1α-KO tumor cells using in vitro wound healing assays, we observed a marked reduction in migratory potential compared with WT clones." (PMID 31666928, 2019).
tumor (continued). "Furthermore, when assessed in a series of wound healing assays, we observed that ERO1α-KO tumor cells displayed impaired ability to close the injury due to migration rates being reduced by half relative to ERO1α-competent tumor cells." (PMID 31666928, 2019). "When administered by subcutaneous (s.c) injection, ERO1α-competent tumors developed readily within just 2 weeks of cell transfer, whereas ERO1α-deficient cancer cells failed to drive tumor formation in recipient animals (n = 6 per group)." (PMID 31666928, 2019). "Having detected a clear impact of ERO1α deletion on PDA cell expression of a key protein regulator of tumor development, we next investigated whether ERO1α was also required to induce other critical mediators of disease progression." (PMID 31666928, 2019). "In addition, some studies have suggested that ERO1α is upregulated under hypoxia in cancer cell lines and tumours." (PMID 31142270, 2019). "Previous studies showed that ERO1α is overexpressed in multiple kinds of cancers, and is involved in tumor biological procession and immune escape, however, its impact on HCC remains unknown." (PMID 30377291, 2018). "Further experiments indicated that ERO1α promoted tumor angiogenesis and positively correlated with VEGF-A expression via the S1PR1/STAT3/VEGF-A pathway, suggesting that ERO1α may be a novel therapeutic target for inhibiting tumor angiogenesis." (PMID 30377291, 2018). "And it has been found that ERO1-α is overexpressed in a variety of tumor types." (PMID 28881752, 2017). "We also immunostained the excised tumours, and the results showed that ERO1α-positive cells in the WT group were confined to the margin of the tumour and the area near sites of necrosis; this staining is generally within a region that is considered to be low in oxygen." (PMID 28839225, 2017). "In addition, knockout of ERO1α sensitized cells to ferroptosis and reduced tumor growth." (PMID 41226317, 2025). "Furthermore, recent evidence suggests that ERO1α upregulation may contribute to increased PD-L1 expression on tumor cells, further dampening T-cell activity and reinforcing immune evasion mechanisms." (PMID 41226317, 2025). "However, it is currently unclear whether expression of ERO1A will be sufficient to determine whether a tumor is sensitive to treatment with an ERO1A inhibitor." (PMID 39496753, 2024). "Therefore, ERO1α positively regulates angiogenesis and tumor growth driven by mTORC1 activation." (PMID 38610018, 2024). "The data above revealed that ERO1α significantly contributed to tumor progression and ferroptosis resistance, encouraging us to explore whether inhibition of ERO1α in combination with ferroptosis inducers could synergistically inhibit the growth of mTORC1-activated cells in vivo." (PMID 38610018, 2024). "Moreover, the expression of ERO1α promoted tumor growth by augmenting angiogenesis." (PMID 38610018, 2024). "Thus, ERO1A signaling limits clinical outcomes and anti-tumor immunity in human cancers." (PMID 37769655, 2023). "Furthermore, we identified SPP1 as the specific signaling pathway involved in the intercellular crosstalk between tumor cells and CD8+ T cells associated with Ero1aWT tumors; however, the rigid cell-to-cell interactions within the ERO1A-associated TME remodeling require more functional studies." (PMID 37769655, 2023). "Therefore, the role of ERO1-α in tumor-mediated immunosuppression should be further explored." (PMID 28160557, 2017). "This review discusses the role of the ERO1α-PDI system in cancer development through the regulation of oxidative stress, redox homeostasis, and tumor plasticity." (PMID 41751162, 2026). "The IHC results showed that ERO1A, CCT6A, and SHC1 were significantly overexpressed in tumor tissues compared to normal samples." (PMID 40953006, 2025).